ERAP2 (endoplasmic reticulum aminopeptidase 2)
Diseases named in the same sentence as ERAP2 in open-access papers (continued):
Sharing a sentence is not in itself a finding about the gene and the disease.
psoriasis (18 papers, 2018 to 2025). An autoimmune condition characterized by red, well-delineated plaques with silvery scales that are usually on the extensor surfaces and scalp. "Other validated psoriasis susceptibility genes were ERAP2 (5q15), IL18R1 (2q12.1), LTB (12p13.31), IL1RL1 (2q12.1), CARD14 (17q25.3), and SLC9A4 (2q12.1)." (PMID 36425068, 2022). "Together, these results showed that the protective haplotype (rs2549797-G and rs2248374-G) almost certainly caused NMD to decrease ERAP2 gene expression, which appeared to reduce the risk of psoriasis." (PMID 31969149, 2020). "ERAP2 is associated with several immune-mediated diseases, including ankylosing spondylitis, psoriasis, and Crohn's disease." (PMID 32596278, 2020). "An identified variant, rs2549797, was highly linked with psoriasis risk SNP rs2910686 (r2 = 0.8051) and located near the 5′ canonical splice site of ERAP2 gene exon 15, forming a new splice site." (PMID 31969149, 2020). "A recent study on treatment response to the IL-17 A antibody Secukinumab in psoriasis patients demonstrated that ERAP2 deficient patients (as indicated by carrying the rs2248374 G/G genotype) had a 6-fold increased risk of treatment failure compared to ERAP2 proficient patients." (PMID 39123229, 2024). "Among other conditions where associations of ERAP2 presence versus absence were observed, we may also list psoriasis, Crohn’s disease, hypertension, and birdshot chorioretinopathy." (PMID 35769458, 2022). "ERAP2 variants are associated with various immune diseases, including psoriasis." (PMID 31969149, 2020). "Since the risk allele of rs2910686 (C) was the same as in AS this result suggests that, like in AS, ERAP2 expression may predispose to psoriasis, although the effect may often be masked by ERAP1." (PMID 30425713, 2018). ",189,190,191ERAP1 and ERAP2 are prominent risk factors in MHC-I linked AI conditions and both are associated with psoriasis risk." (PMID 37339630, 2023). "In this study, we verified the psoriasis susceptibility genes IFIH1 (2q24.3), ERAP2 (5q15), IL18R1 (2q12.1), LTBR (12p13.31), IL1RL1 (2q12.1), CARD14 (17q25.3), and SLC9A4 (2q12.1)." (PMID 36425068, 2022). "SFRP2+ fibroblasts were reported to overexpress ERAP2 and HLA-C in psoriasis." (PMID 40574847, 2025). "AS belongs to the so-called “MHC-I-opathies”, together with the psoriasis, Behçet’s disease, birdshot uveitis and acute anterior uveitis for which GWAS have highlighted the association to ERAP1 and, sometimes, ERAP2, apart from the involvement of a key specific HLA-class I gene." (PMID 37686141, 2023). "ERAP2 was established upon controlling for the contribution of ERAP1 in psoriasis." (PMID 34395615, 2021). "The main issues addressed in our study were: (i) whether smokers and never-smokers differ in the associations of APM polymorphisms with NSCLC risk and clinical outcome, (ii) whether ERAP2 influences the ERAP1 effect, if any, as we observed it in other diseases—psoriasis, and ankylosing spondylitis." (PMID 34149699, 2021). "ERAP2 is associated with AS and psoriasis, but not in epistasis with MHC-I." (PMID 30425713, 2018). "PSORS (psoriasis-susceptibility) loci harbor several genes that are involve in psoriasis; for example, HLA-Cw6, ERAP1, ERAP2, and MICA are involved in antigen presentation." (PMID 32671018, 2020). "Another study mapped eQTLs in skin tissues from psoriasis patients and looked at overlap with psoriasis GWAS results, finding significant enrichment of psoriasis GWAS SNPs in their eQTL dataset, with effects on the expression of genes such as FUT2, RPS26 and ERAP2." (PMID 32778885, 2020). "Defining the association of ERAP2 with psoriasis has been complicated due to the seemingly non-epistatic nature of this association, the heterogeneity of the disease and the apparently opposite effects of ERAP1 and ERAP2 in the same haplotype, leading to a masking of the latter by ERAP1." (PMID 30425713, 2018).
Crohn disease (11 papers, 2012 to 2025). A gastrointestinal disorder characterized by chronic inflammation involving all layers of the intestinal wall, noncaseating granulomas affecting the intestinal wall and regional lymph nodes, and transmural fibrosis. "The presence of rs2549794-C allele results in increased production of ERAP2 protein, improving the immune response to Yersinia pestis and contributing to the risk of developing Crohn’s disease in contemporary populations." (PMID 41428259, 2025). "Genetic variants that reside in haplotype A of the ERAP2 gene predispose to a variety of severe inflammatory conditions, including among others, Crohn’s disease, ankylosing spondylitis, birdshot chorioretinopathy, and Juvenile idiopathic arthritis." (PMID 37925533, 2023). "Variants associated with changes in ERAP2 isoforms have previously been shown to increase Crohn’s disease risk upon immune stimulation." (PMID 38102153, 2023). "At baseline and following type 1 interferon stimulation, the major haplotype is associated with low ERAP2 expression caused by nonsense-mediated decay, while the minor haplotype, known to increase Crohn's disease risk, is associated with high ERAP2 expression." (PMID 30446528, 2018). "A functional polymorphism in the gene (rs30187, Arg528Lys) associates with susceptibility to ankylosying spondylitis (AS), whereas a SNP in the interacting ERAP2 gene increases susceptibility to another inflammatory autoimmune disorder, Crohn's disease (CD)." (PMID 22253828, 2012). "ERAP2 was also associated with susceptibility to Crohn’s disease." (PMID 34570765, 2021). "We assess the burden of functionally impactful variants present in ERAP1 and ERAP2 in 2 cohorts of patients diagnosed with inflammatory bowel disease (IBD; Crohn’s disease (CD) or ulcerative colitis (UC))." (PMID 41428259, 2025). "For example, we identified response 3′aQTLs for ERAP2, which were co-localized with Crohn’s disease for the CD4T-cells and R848 stimulation conditions." (PMID 38102153, 2023). "In blood, there was a highly significant (FDR corrected P = 1.27 × 10− 131) association between rs2549794 at a Crohn's disease locus and expression of ILMN_1743145, which maps to the LRAP/ERAP2 gene." (PMID 22433082, 2012).
Autoimmunity (10 papers, 2012 to 2025). The occurrence of an immune reaction against the organism's own cells or tissues. "ERAP1 and ERAP2 single nucleotide polymorphisms (SNPs) have been connected to autoimmune disorders as well as to the susceptibility to bacterial and viral infections, including COVID-19." (PMID 37218755, 2023). "Recent genome-wide association studies have identified common variants of ERAP1 and ERAP2 linked to several human diseases, ranging from viral infections to autoimmunity and cancer." (PMID 22942706, 2012). "Suboptimal antigens generated by altered ERAP1 and ERAP2 could trigger responses to commensal instead of pathogenic bacteria resulting in a chronically inflamed state or auto-antigen presentation resulting in autoimmunity." (PMID 41428259, 2025). "This pathway also includes the ER aminopeptidase encoded by ERAP2 and the leukocyte immunoglobulin-like receptor subfamily B member 1 (LILRB1) gene, a gene associated with familiar autoimmunity." (PMID 40883722, 2025). "It has been suggested that an individual’s ERAP variant must generate autoantigenic peptides capable of stimulating pathogenic autoreactive T cells, in addition to the ratio of ERAP2 to ERAP1 favouring autoantigen processing for autoimmunity to occur." (PMID 38898675, 2024). "Together, these data highlight several mechanisms linking ERAP2 loss to PTSD and CVD, along with autoimmunity, ER stress, impaired autophagy, thymic involution, dysfunctional OXT processing, and loss of ANG IV." (PMID 37218755, 2023). "We surmise that ERAP2 protects against PTSD and CVD and that loss of this protein drives thymus-mediated autoimmunity, predisposing to these pathologies." (PMID 37218755, 2023). "We have narrowed down the potential sequences for autoimmunity-inducing antigenic peptides based on the selective effect of ERAP2 on the peptide cargo of HLA-A29 in the pathogenesis of Birdshot Uveitis." (PMID 33717175, 2021). "The same authors surmise that ERAP2 resilience to plague may have contributed to the development of modern diseases, including autoimmunity." (PMID 37218755, 2023). "Although most HLA-associated autoimmune conditions have shown strong linkage with ERAP1, BSCR and the linkage with ERAP2 expression may highlight a role for ERAP2 in controlling the generation or destruction of specific epitopes for HLA-A*29:02." (PMID 30054427, 2018). "Existing functional evidence suggests that this could be through the production of full length functional ERAP2 protein resulting in an enhanced response to infection and autoimmunity, or through the regulation of gene expression in CD4 + T cells, resulting in immune dysregulation." (PMID 41428259, 2025). "This could imply that, in B*27:05 carriers, the same genetic allelic variants of ERAP1 and ERAP2 not predisposing to autoimmunity do not favour the presentation of uncanonical viral peptides as well." (PMID 37686141, 2023).
ankylosing spondylitis (9 papers, 2020 to 2024). An autoimmune chronic inflammatory disorder characterized by inflammation in the vertebral joints of the spine and sacroiliac joints. "The purpose of this study was to determine the genetic association between ERAP2 gene rs2910686, and rs2248374 single nucleotide polymorphisms (SNPs) and the risk of ankylosing spondylitis in the Egyptian population." (PMID 38704785, 2024). "ERAP2, specifically in the form of rs2910686 variant, was identified in 2013 as an independent risk factor for developing Ankylosing Spondylitis in HLA-B27-negative patients." (PMID 38892265, 2024). "Several groups of researchers examined the role of ERAP1 and ERAP2 as ankylosing spondylitis risk factors in addition to HLA-B*27 (reviewed by 17, 18, 26, 56–58)." (PMID 35769458, 2022). "Ankylosing spondylitis (AS) is often regarded as the prototypical manifestation of spondylo-arthropathies that prevalently involves the axial skeleton with the potential attribution of ERAP2 polymorphisms to AS predisposition." (PMID 38704785, 2024). "The association of Ankylosing Spondylitis with aminopeptidases located either inside the endoplasmic reticulum (ER)—such as ERAP1, ERAP2, and LNPEP —or in the cytoplasm—specifically NPEPPS —highlights the importance of this process." (PMID 38892265, 2024). "Therefore, the lack of active ERAP2 enzyme in allotype B homozygotes results in changes in the immunopeptidome, as it was shown for HLA-B*27, associated with ankylosing spondylitis." (PMID 35769458, 2022).
inflammatory bowel disease (7 papers, 2018 to 2025). A spectrum of small and large bowel inflammatory diseases of unknown etiology. "ERAP2 is an aminopeptidase involved in antigen processing and presentation, and harbor genetic variants linked to several inflammatory diseases such as Inflammatory Bowel Disease (IBD)." (PMID 39123229, 2024). "Similarly, polymorphisms in ERAP2 have been associated with diverse conditions, including inflammatory bowel disease and viral infections." (PMID 40226591, 2025). "These include ATP13A1 with BMI, ERAP2 for both inflammatory bowel disease and celiac disease, RPS26 for both type 1 diabetes and rheumatoid arthritis, and BTN2A1 with schizophrenia." (PMID 30061686, 2018). "Indeed, plasma levels of ERAP1 and ERAP2 have been recently reported as markers of disease severity in inflammatory bowel diseases, preeclampsia, ankylosing spondylitis, and hepatitis B infection." (PMID 40226591, 2025).
influenza (7 papers, 2018 to 2025). An acute viral infection of the respiratory tract, occurring in isolated cases, in epidemics, or in pandemics; it is caused by serologically different strains of viruses (influenzaviruses) designated A, B, and C, has a 3-day incubation period, and usually lasts for 3 to 10 days. "We provide evidence of the expression of short ERAP2 isoforms encoded by Haplotype B in response to influenza, suggesting viral infection as a possible selective agent." (PMID 30446528, 2018). "ERAP2 encodes a zinc metalloaminopeptidase involved in antigenic response and polymorphisms at this locus are responsible for differential response to bacterial infection and influenza." (PMID 34570765, 2021). "The influenza-dependent genetic control of ERAP2 isoform usage is supported by two additional lines of evidence." (PMID 30446528, 2018). "In order to verify if the expression of ERAP2/Iso3 may be induced by other pathogens, PBMCs and MDMs isolated from 20 healthy subjects were stimulated with flu, LPS, CMV, HIV-AT-2, SARS-CoV-2 antigens to analyze its mRNA and protein expression." (PMID 32847031, 2020). "Following influenza infection, rs2248374-G ERAP2 expressing cells may transcribe an alternative spliced isoform: ERAP2/Iso3." (PMID 32847031, 2020). "This was clearly demonstrated at the ERAP2 locus, where multiple variants result in differential expression and splicing of short isoforms in response to influenza but not interferon." (PMID 30446528, 2018). "Indeed, an analysis recently conducted on dendritic cells carrying the G allele of this SNP revealed that two previously unknown short isoforms (ERAP2/ISO3, ERAP2/ISO4) are transcribed from this haplotype following influenza infection, thanks to the creation of a different preferred splice site." (PMID 32183384, 2020).
melanoma (7 papers, 2012 to 2023). A malignant, usually aggressive tumor composed of atypical, neoplastic melanocytes. "Renal carcinoma, colon adenocarcinoma, melanoma, and ovarian cancer show less ERAP2, suggesting that ERAP2 expression harms cancer progression." (PMID 36834865, 2023). "ERAP1 and ERAP2 expression is also frequently altered in melanoma, acute myeloid leukemia, gastric adenocarcinoma, HPV-induced malignancies and renal clear cell carcinoma, as another immune escape mechanism." (PMID 33499248, 2021). "In another study, a heterogeneous expression of ERAP1 and ERAP2 was detected in a panel of 28 melanoma cell lines." (PMID 25566501, 2014). "In one study, expression of ERAP1 and ERAP2 was detected in all tumor cell lines examined, including melanoma and various type of carcinomas, although at highly variable levels and independently of each other." (PMID 25566501, 2014). "In a recent study, heterogeneous expression of ERAP1 and ERAP2, ranging from high to very low levels, was detected in 28 melanoma cell lines as compared to primary melanocytes." (PMID 22942706, 2012). "We found that ERAP1 and ERAP2 were expressed in essentially all tumor cell lines examined (melanomas, leukemia-lymphomas and carcinomas of breast, colon, lung, chorion, skin, prostate, cervix, kidney and bladder) at highly variable levels and independently of each other." (PMID 22942706, 2012). "Moreover, this study may explain the imbalance between ERAP1 and ERAP2 observed in various tumor cell lines, such as leukemia, lymphoma, carcinoma, and melanoma, and in tumor-transformed tissues of the breast, ovary, lung, colon, and thyroid." (PMID 37372322, 2023).
pancreatic cancer (7 papers, 2017 to 2025). "As a risk factor, ERAP2 expression is positively relevant to the risk value of pancreatic cancer patients, and is more suitable as a target for further research." (PMID 36214762, 2022). "Indeed, Yu and colleagues observed exceptionally higher ERAP2 levels in pancreatic tumors compared to normal tissues, which were associated with poor prognosis in pancreatic cancer patients." (PMID 40226591, 2025). "In summary, we found that ERAP2, a previously unreported biomarker, predicts sensitivity to gemcitabine in patients with pancreatic cancer, possibly acting in part through the PI3K/AKT/mTOR signaling pathway." (PMID 36214762, 2022). "Overall, our results suggest that down-regulation of ERAP2 significantly blocks the tumorigenic ability of pancreatic cancer cells and significantly enhances the anti-pancreatic cancer activity of gemcitabine." (PMID 36214762, 2022). "We next identified the tumorigenesis and sensitivity of pancreatic cancer cells to gemcitabine after ERAP2 knockdown." (PMID 36214762, 2022). "It was indicated that ERAP2 knockdown significantly restrained the growth of pancreatic cancer cells." (PMID 36214762, 2022). "Compared with gemcitabine alone, knockdown ERAP2 combined with gemcitabine further reduced the migration ability of pancreatic cancer cells, and the invasion ability was more significantly inhibited." (PMID 36214762, 2022). "According to the previous study, FYN, LRSAM1, and SEMA6C serve as poor prognostic biomarkers in pancreatic cancer, whereas ERAP2, MET, IL20RB, and CXCL11 indicate improvements." (PMID 36428747, 2022). "The development of ERAP2 inhibitors will further expand the therapeutic options for pancreatic cancer, and provide strategies for gemcitabine combination therapy." (PMID 36214762, 2022). "We downloaded the expression microarray GSE62452 from GEO database of pancreatic tumors and paracancerous tumors, and found that ERAP2 was highly expressed in pancreatic tumors." (PMID 36214762, 2022). "However, ERAP2-induced cellular migration and metastasis formation seem to be equally relevant in the onset and progression of pancreatic cancer." (PMID 40226591, 2025). "Notably, inhibiting ERAP2 through knockdown techniques not only suppressed tumor growth but also augmented the efficacy of gemcitabine, frontline chemotherapy for pancreatic cancer, inhibiting cancer cell proliferation, migration, and invasion." (PMID 40226591, 2025). "Specifically, it will be extremely interesting to assess whether subjects who are natural knockouts for ERAP2 expression, because of the rs2248374 polymorphism, display a different susceptibility/progression to OSCC or pancreatic cancer." (PMID 40226591, 2025). "Moreover, ERAP2 knockdown was shown to weaken the capacity of PSCs to promote migration and invasion of pancreatic cancer cells." (PMID 39839670, 2024). "In addition, we performed a Kaplan-Meier survival analysis in the TCGA pancreatic cancer dataset, using the median expression of ERAP2 as the threshold." (PMID 36214762, 2022). "Furthermore, we demonstrated that knockdown of ERAP2 significantly improved the killing effect of gemcitabine on pancreatic cancer cells." (PMID 36214762, 2022). "In clinical treatment, it is reasonable to consider that gemcitabine combined with ERAP2 inhibitor may improve the sensitivity of pancreatic cancer patients to gemcitabine." (PMID 36214762, 2022). "Additionally, ERAP2 knockdown suppressed tumorigenesis and potentiated gemcitabine-induced growth, migration and invasion inhibition in human pancreatic cancer cells." (PMID 36214762, 2022). "We conclude that ERAP2 expression may play an important role in the sensitivity of pancreatic cancer cells to gemcitabine." (PMID 36214762, 2022). "In addition, ERAP2 was also significantly overexpressed in blood extracellular vesicle samples of pancreatic cancer patients from the BBCancer database." (PMID 36214762, 2022).